LRRC37B (leucine rich repeat containing 37B)
Synonyms: LRRC37
Tractability: Antibody: UniProt predicts a signal peptide or a membrane-spanning region. PROTAC: ubiquitination databases record sites on it.
Gene: Protein-coding gene on chromosome 17 (32,007,383 to 32,053,504, forward strand). Ensembl gene ENSG00000185158.
Subcellular location: Membrane
Subcellular location (Human Protein Atlas): Cytosol
Gene Ontology:
Cellular component: membrane
Genetic constraint (gnomAD): Loss-of-function variants: 23 observed, 79.52 expected, observed/expected ratio (o/e) 0.29, 90% interval 0.21 to 0.41. The upper end of that interval is the gene's LOEUF score, 0.41, which puts it in group 1 of 6, group 1 being the genes least tolerant of losing a copy. Missense variants: 879 observed, 1,070.9 expected, observed/expected ratio (o/e) 0.82, 90% interval 0.78 to 0.87. Synonymous variants: 337 observed, 401.58 expected, observed/expected ratio (o/e) 0.84, 90% interval 0.77 to 0.92.
Homologues: Orthologues: macaque LRRC37A (60% identical), rat Prp2l1 (49% identical), mouse Lrrc37a (49% identical), mouse Lrrc37 (48% identical), rat Lrrc37a (40% identical). Paralogues in human: LRRC37A (73% identical), LRRC37A2 (73% identical), LRRC37A3 (73% identical).
Diseases named in the same sentence as LRRC37B in open-access papers:
LRRC37B is named in the same sentence as 3 diseases in open-access papers, as found by Europe PMC text mining. Sharing a sentence is not in itself a finding about the gene and the disease. The quoted sentences say what the papers report.
infection (1 paper, 2025). The state of being infected such as from the introduction of a foreign agent such as serum, vaccine, antigenic substance or organism. "As the immediate neighboring protein-coding genes, RHOT1 and LRRC37B, were not identified in this round of RNA-seq, it seems unlikely that VILMIR regulates these genes during infection." (PMID 40130878, 2025).
LRRC37B also shares sentences with these, for which no sentence is quoted: infertile (1 paper); learning disability (1).